ADAMTS5 (ADAM metallopeptidase with thrombospondin type 1 motif 5)
Diseases named in the same sentence as ADAMTS5 in open-access papers (continued):
Sharing a sentence is not in itself a finding about the gene and the disease.
intervertebral disc degeneration (8 papers, 2009 to 2023). "An important factor promoting intervertebral disc degeneration is the special metalloproteinase gene ADAMTS-5." (PMID 37968507, 2023). "RREB1 has been reported to regulate renin-angiotensin system by inhibiting hANG 27 and to participate in the intervertebral disc degeneration protection by inhibiting the expression of ADAMTS5." (PMID 32210733, 2020). "A dominant imbalance of MMP-3/TIMP-1 and TIMP-2 relative to ADAMTS-4 and ADAMTS-5/TIMP-3 signifies an advanced stage of intervertebral disc degeneration." (PMID 22394620, 2012). "ADAMTS-5 thus has the potential to play a role in intervertebral disc degeneration; however, further investigations are needed." (PMID 22394620, 2012). "The purpose of this study was to evaluate the suppressive effects of injections of ADAMTS5 small interference RNA (siRNA) oligonucleotide on intervertebral disc degeneration in the rabbit anular needle-puncture model." (PMID 19889209, 2009). "Integrated with these reports, our findings show that a state of dominant MMP-3/TIMP-1 and TIMP-2 imbalance relative to ADAMTS-4 and ADAMTS-5/TIMP-3 imbalance may indicate an irreversible stage of intervertebral disc degeneration." (PMID 22394620, 2012). "In a static pressure-induced rat model with caudal intervertebral disc degeneration, the mRNA levels of ADAMTS4, ADAMTS5, ADAMTS7, and ADAMTS12 were found to be increased significantly." (PMID 32855969, 2020). "A dominant imbalance of MMP-3/TIMP-1 and TIMP-2 relative to ADAMTS-4 and ADAMTS-5/TIMP-3 is a possible indication of an advanced, irreversible stage of intervertebral disc degeneration." (PMID 22394620, 2012).
glioblastoma (7 papers, 2017 to 2025). The most malignant astrocytic tumor (WHO grade IV). "A high expression level of ADAMTS5 promotes the invasion and migration of human glioblastoma, non-small-cell lung cancer, and HNSCC cells." (PMID 32884571, 2020). "In this regard, degradation of two well-known ADAMTS-5 substrates such as brevican and aggrecan facilitate tumor progression in glioblastoma and laryngeal carcinoma, respectively." (PMID 28099917, 2017). "The effect of SNPs on expression from eQTL studies from HaploReg suggested that only rs2830585 was associated with altered expression of ADAMTS5 in human glioblastoma cell line U87MG, no promoter histone marks and enhancer histone marks were found in these variants." (PMID 30369484, 2018). "In human glioblastomas, secretory proteases, such as ADAMTS4 and ADAMTS5, are expressed at the mRNA and protein levels in considerable amounts." (PMID 36980765, 2023).
glioma (7 papers, 2007 to 2021). A benign or malignant brain and spinal cord tumor that arises from glial cells (astrocytes, oligodendrocytes, ependymal cells). "For instance, brevican cleavage by ADAMTSs has been associated to progression of the gliomas, and an increased expression at both RNA and protein levels of ADAMTS-4 and ADAMTS-5 has been detected in glioblastoma, the most aggressive form of glioma." (PMID 33804223, 2021). "Cleavage of brevican, another member of the lectican family by ADAMTS-5 is functionally involved in glioma invasion in vivo." (PMID 17453002, 2007). "However, other ADAMs with thrombospondin motifs (ADAMTS4, ADAMTS5) positively impacted the proliferation of glioma cells in vitro and potentially promoted their invasion by cleavage of brevican, a major component of brain tissue." (PMID 32346064, 2020). "However, ADAMTS-5 also cooperates with fibulin-3 to promote cell invasion in gliomas through proteolytic degradation of ECM components." (PMID 31508361, 2019). "In addition, EFEMP1 has been shown to be overexpressed concomitantly with MMP-2, MMP-9 and ADAMTS-5 in glioma." (PMID 25987128, 2015). "In glioma, increased EFEMP1expression promotes tumor invasion and progression by modulating the extracellular matrix by increasing the expression of MMP2, MMP9 and ADAMTS-5 via Notch signaling." (PMID 34204134, 2021).
joint disease (7 papers, 2017 to 2026). "Considering the crucial role of ADAMTS-5 in the pathogeneses of joint diseases, inhibition of its expression and production could represent a promising therapeutic strategy for joint inflammatory diseases." (PMID 41020853, 2025). "The rise of ADAMTS-5 concentrations in the control group might be explained by a further progression of joint disease or by the fact that the patients were required to refrain from anti-inflammatory analgesics." (PMID 29246219, 2017). "Supported by recent literature on the roles of MMPs, ADAMTS‐5, and COMP in joint disease, the model offers a valuable platform for future studies on OA mechanisms and therapeutic screening." (PMID 41272411, 2026). "Moreover, in Ctsk(-/-) knockout mice with OA induced by joint instability, disease progression was significantly delayed, while the expression levels of other proteases (such as MMP13 and ADAMTS5) decreased compared to the control group." (PMID 36233118, 2022). "Our results suggest that unlike ADAMTS-4 and ADAMTS-5, which are widely recognised as destructive aggrecanases in joint disease, the aggrecanolytic activity of ADAMTS-9 might be more important for normal joint development than for pathology." (PMID 30699963, 2019).
knee osteoarthritis (7 papers, 2021 to 2026). "Gene sequencing was performed using iPLEX Gold to determine the association between the gene polymorphism of ADAMTS5 rs226794 and knee osteoarthritis." (PMID 34946864, 2021). "The limited selectivity of most catalytic-site ADAMTS-5 inhibitors and the necessity to preserve aggrecan integrity in early-grade knee osteoarthritis require the development of selective aggrecanase inhibitors." (PMID 41900115, 2026). "This study aims to assess the efficacy of the anticatabolic ‘a disintegrin and metalloproteinase with thrombospondin motif-5’ (ADAMTS-5) inhibitor, S201086/GLPG1972, in slowing cartilage loss in participants with knee osteoarthritis (OA)." (PMID 36474770, 2021). "ADAMTS-5 is a promising target for the identification of knee osteoarthritis (KOA)." (PMID 34889297, 2021).
melanoma (6 papers, 2006 to 2025). A malignant, usually aggressive tumor composed of atypical, neoplastic melanocytes. "In this work, we demonstrate that systemically delivered rTSR1 of ADAMTS5 via IP injection potently suppressed distant subcutaneous melanoma growth in mice." (PMID 29891754, 2018). "Finally, ADAMTS5's recombinant TSR1 inhibits the growth of melanoma in mice by anti-angiogenesis mechanism, and ADAMTS5 can also be used as a prognostic biomarker for prostate cancer." (PMID 33123466, 2020). "Studies show that the expression of Timp2 (tissue inhibitor of metalloproteinase 2), Timp3 (tissue inhibitor of metalloproteinase 3) and Adamts5 (a disintegrin-like and metalloproteinase with thrombospondin type 1 motif, 5) reduce angiogenesis in melanoma cells." (PMID 31591386, 2019). "Of the genes correlated with shorter survival, some were already known to be over-expressed in different types of cancer, such as MCM3, BCHE, and some have previously been implicated in melanoma progression, like CSPG4 and Cx26 or, more generally, associated with tumor invasiveness, like ADAMTS5." (PMID 17129373, 2006). "Our data indicate that loss of CYLD contributes to angiogenesis in melanoma by a potential negative effect on expression of several anti-angiogenic factors like TIMP-2, TIMP-3 and ADAMTS5." (PMID 31591386, 2019). "Indeed, it resulted quite appealing the fact that such positive association did occur with high expression of other ADAMTS proteases (ADAMTS2, ADAMTS4, ADAMTS5, ADAMTS9, ADAMTS12 and ADAMTS14) that definitively implied a key role of these proteases during melanoma progression." (PMID 32230715, 2020).
lung cancer (5 papers, 2023 to 2025). A malignant neoplasm involving the lung. "In lung cancer, the expression of Adamts5 is up-regulated, which can promote the migration and invasion of tumor cells." (PMID 36902425, 2023). "For example, ADAMTS5 was upregulated in NSCLC tissues and enhances the migration and invasion of lung cancer cells." (PMID 36947712, 2023).
prostate carcinoma (5 papers, 2012 to 2020). A carcinoma that arises from epithelial cells of the prostate gland. "Another study has shown that ADAMTS5 transcript was below detectable limit in prostate cancer cell lines PC3, DU145 and LnCaP." (PMID 24213506, 2012). "Additionally, decreased ADAMTS-5 expression was observed in prostate cancer and coincided with the accumulation of versican." (PMID 32923459, 2020). "In this study, we identified several genes including the cytokines Il-6, Tgfb2, Cxcl1, and Ctgf, metallopeptidases Mmp13, Adamts1, Adamts4, and Adamts5, and transcription factors Junb, Fos, Stat3 and Cebpb that were up-regulated in osteoblasts as a result of prostate cancer–osteoblast interactions." (PMID 27600237, 2015). "Down-regulation of ADAMTS5 mRNA in prostate cancer cell lines." (PMID 24213506, 2012).
tendinopathies (5 papers, 2013 to 2022). "There are similarities in our findings to what has been observed in overuse tendinopathies in humans such as downregulation of ADAMTS-5 mRNA." (PMID 36553476, 2022). "Increased proteoglycan deposition in tendon disease correlates with ADAMTS5 knockout and with its reduced expression in human tendinopathy." (PMID 24086616, 2013). "ADAMTS5 was chosen as it responded differently to mechanical load and TGFβ, unlike many of the other genes, and it has also been shown to be regulated in tendinopathy." (PMID 23830915, 2013). "Given that impaired mechanical loading increases MMP1 and ADAMTS5 in synovial cells, our results might partly reflect the upregulation of mechanical stress factors due to tendinopathy." (PMID 35168639, 2022). "However, MMP1, MMP13, MMP10, ADAMTS5, TIMP3, versican, aggrecan, biglycan, decorin, fibronectin, fibrillin and COMP showed an opposite response with strain compared to tendinopathy." (PMID 23830915, 2013).
cerebral cavernous malformation (4 papers, 2020 to 2026). A disorder characterized by malformations in the structure of the capillaries in the brain. "Recent studies have identified MMP-16 as a schizophrenia risk gene, and MMP-9 and ADAMTS-5 are implicated in schizophrenia and cerebral cavernous malformations, respectively." (PMID 33143303, 2020). "However, expression of ADAMTS5 in brain endothelial cells of Ccm2-deficient mice aggravated cerebral cavernous malformation (CCM) lesion burden and shortened the life span of Ccm2-deficient mice." (PMID 42144952, 2026). "It was also recently shown that proteolysis of versican by ADAMTS-5 constitutes a downstream mechanisms of the cerebral cavernous malformations (CCM) pathogenesis." (PMID 33804223, 2021).
gastric cancer (4 papers, 2015 to 2025). A primary or metastatic malignant neoplasm involving the stomach. "However the previous studies also reported that Adamts5 plays an anticancer role by inhibiting migration, invasion, and angiogenesis of gastric cancer cells (GC)." (PMID 36902425, 2023).
Obesity (4 papers, 2016 to 2024). Accumulation of substantial excess body fat. "PPARG, ADAMTS5, TIMP4, ANXA1, AGTR1, and CXCL12 genes are evidently associated with obesity, suggesting that the influence of these genes on obesity may be similar to the influence of fat accumulation in hMSCs." (PMID 34899844, 2021). "Thus, neutralization of ADAMTS5 could be a potentially interesting strategy to combat obesity and to improve metabolic health." (PMID 29293679, 2018). "THBS1 is required for this shift, since the expression of numerous obesity-induced, ECM-related FAP genes (such as Fbn1, Col3a1, and Adamts5) is markedly blunted in HFD-fed KO mice." (PMID 38954467, 2024). "Using this approach we have identified the nuclear hormone receptor PPARG, the metalloproteinase ADAMTS5, and the aldo-keto reductase AKR1B10 as potential drug targets for treatment of osteoporosis and obesity." (PMID 27562730, 2016).
ovarian cancer (4 papers, 2018 to 2025). A primary or metastatic malignant neoplasm involving the ovary. "More recently, ADAMTS5 has been implicated in ovarian cancer (OC), due to its essential role in promoting cell migration and association with poor prognosis." (PMID 41381706, 2025). "ADAMTS5, in particular, is a secreted protease targeting proteoglycans that has demonstrated divergent roles across cancer types—protective in human hepatocellular carcinoma, melanoma, and cancers of the digestive apparatus, yet associated with poor prognosis in ovarian cancer." (PMID 40406984, 2025). "Recently, we have shown that ADAMTS5 expression is necessary and sufficient to stimulate migration of ovarian cancer (OC) cells and that is correlated with poor prognosis in OC patients." (PMID 41381706, 2025). "We found that the small GTPase Rab25 promoted the expression of ADAMTS5 in ovarian cancer cells, through the activation of the NF‐κB signalling pathway." (PMID 40164572, 2025). "The native matrix produced by CAFs, synergizing with an upregulation of the small GTPase Rab25 often present in ovarian cancer cells, triggered a robust increase in the secretion of ADAMTS5, driven by NF‐κB‐dependent transcriptional activation." (PMID 40406984, 2025). "In another study, a higher ADAMTS-1, ADAMTS-5, aggrecan, versican and TIMP-3 expression in malignant ovarian tumors compared to benign tumors was associated with a shorter overall survival in ovarian cancer patients." (PMID 29393911, 2018). "In particular, ADAMTS5 has been reported to be upregulated in ovarian malignant tumours compared to borderline and benign lesions, suggesting it might play a role in metastatic progression." (PMID 40164572, 2025). "Furthermore, ADAMTS5 was necessary and sufficient to stimulate ovarian cancer cell migration through complex fibroblast‐secreted matrices, while selective ADAMTS5 inhibition prevented ovarian cancer spheroid invasion in 3D systems." (PMID 40164572, 2025). "However, it is not clear why there was a parallel increase in TIMP-3 expression, the tissue inhibitor of ADAMTS-1 and ADAMTS-5, in malignant ovarian neoplasms compared to benign epithelial ovarian neoplasm." (PMID 29393911, 2018). "Furthermore, it has been suggested that Rab25, a small GTPase of the Ras family, might upregulate ADAMTS5 expression in ovarian cancer cells." (PMID 40164572, 2025). "Finally, in ovarian cancer patients, high ADAMTS5 expression correlated with poor prognosis." (PMID 40164572, 2025). "Altogether, these data identify ADAMTS5 as a novel regulator of ovarian cancer cell migration and invasion, suggesting it might represent a previously undescribed therapeutic target to prevent ovarian cancer metastasis." (PMID 40164572, 2025). "Thus, ADAMTS5 is a novel regulator of ovarian cancer cell migration and invasion, suggesting it might represent a previously undescribed therapeutic target." (PMID 40164572, 2025).
rheumatoid arthritis (4 papers, 2014 to 2022). A chronic, systemic autoimmune disorder characterized by inflammation in the synovial membranes and articular surfaces. "EQ decreased gene expression of MMP-13 and ADAMTS-5 in rheumatoid arthritis and inhibited the NF-κB signaling pathway in mouse macrophages." (PMID 36311191, 2022). "In a rheumatoid arthritis mouse model, the IKKα-dependent non-canonical heterodimer relB-p52 enhances the transcriptional activity of NOTCH and Rbpj, required for the transcription of ADAMTS5 and MMP-13." (PMID 34769441, 2021).
breast tumor (3 papers, 2017 to 2025). "ADAMTS5 is overexpressed in invasive breast tumors; it promotes extracellular matrix degradation, aiding tumor progression and metastasis." (PMID 40565055, 2025). "Immunohistochemical analysis highlights the close proximity or partial overlap of both Fibulin-2 and ADAMTS-5 in breast tumor samples." (PMID 28099917, 2017). "Six breast tumor samples corresponding to advanced stages of the disease were additionally analyzed and a weak signal corresponding to the entire Fibulin-2 was detected in three samples and ADAMTS-5 was identified in most of them." (PMID 28099917, 2017).
liver cancer (3 papers, 2017 to 2025). An epithelial or non-epithelial malignant neoplasm that arises from the liver. "The role of ADAMTS5 in digestive system tumors is unclear, but its expression level was confirmed to be low in GC, colon cancer, and liver cancer." (PMID 32884571, 2020). "Additionally, we analyzed the expression of ADAMTS5, CDCA8, and LDHA, the top three high-risk genes, in a liver cancer tissue array comprising 57 paired liver cancer tissues." (PMID 40647517, 2025).
thoracic aortic aneurysm (3 papers, 2019 to 2024). An aneurysm formed in the wall of the proximal portion of the descending aorta proceeding from the arch of the aorta. "Previous murine studies have also suggested the involvement of ADAMTS5 in thoracic aortic aneurysm formation." (PMID 39728917, 2024). "A previous study has demonstrated that deficiency of ADAMTS-5 contributed to a marked reduction of versikine and resulted in aortic ECM remodeling in angiotensin II-induced thoracic aortic aneurysm." (PMID 31929842, 2019).
Alzheimer disease (2 papers, 2005 to 2024). A progressive, neurodegenerative disease characterized by loss of function and death of nerve cells in several areas of the brain leading to loss of cognitive function such as memory and language. "Reduction of the reelin level by ADAMTS-4 and ADAMTS-5-dependent degradation is associated with hyperphosphorylated tau protein, forming neurofibrillary tangles leading to Alzheimer’s disease." (PMID 38980840, 2024).
aneurysm (2 papers, 2018 to 2021). Bulging or ballooning in an area of an artery secondary to arterial wall weakening. "LRP1, which has been involved in aneurysm pathology in both humans and mice, appears to be linked to ADAMTS-5 and ADAMTS-5–mediated versican cleavage." (PMID 29622560, 2018). "The administration of recombinant protein ADAMTS-5 significantly reduced the incidence of aneurysm rupture in the experimental model of IA." (PMID 33934089, 2021). "We found decreased expression of ADAMTS-5 in aneurysmal tissue samples from patients with IA and rADAMTS-5 administration in IA mice reduced arterial matrix degeneration and aneurysm rupture in the cerebral artery using an IA mouse model." (PMID 33934089, 2021). "However, ADAMTS-5 could play a better role in the later stage of pathological progression, and rADAMTS-5 was shown to have a significant impact on the rupture rate of aneurysms." (PMID 33934089, 2021).
cervical cancer (2 papers, 2017 to 2022). A primary or metastatic malignant neoplasm involving the cervix. "These target genes were crossed with mRNAs that are downregulated by more than fivefold in cervical cancer from The Cancer Genome Atlas (TCGA) database, and 8 target genes were finally obtained (OGN, SCN7A, PGR, PTGER3, FGF7, ADAMTS5, LMO3 and ANK2)." (PMID 35513835, 2022).
coronary artery disease (2 papers, 2019 to 2024). "However, the plasma ADAMTS-5 levels and relevance of coronary artery disease (CAD) remain largely unknown." (PMID 31929842, 2019).
diabetes (2 papers, 2022 to 2023). "For example, mutations in Slc38a3 cause overall developmental delay, intellectual disability, hypotonia, and loss of speech, Adamts5 prevents impaired cardiac function by regulating versican degradation, and Cdkn2a/b locus influences the risk of diabetes through both islet and non-islet mechanisms." (PMID 37305038, 2023).
head and neck cancer (2 papers, 2017 to 2025). A primary or metastatic malignant neoplasm affecting the head and neck. "Of note, ADAMTS-4 is expressed at lower level than ADAMTS-5 in tumors of the larynx and in the metastatic loci of head and neck cancers." (PMID 28099917, 2017).